SLC35E2A (solute carrier family 35 member E2A (pseudogene))
Description:
Putative transporter.
Synonyms: KIAA0447; SLC35E2AP; SLC35E2P; formerly SLC35E2
Gene: Transcribed unprocessed pseudogene on chromosome 1 (1,734,690 to 1,739,557, reverse strand). Ensembl gene ENSG00000215790.
Subcellular location: Membrane